TRIM15 (tripartite motif containing 15)
Description:
E3 ubiquitin ligase that plays a role in several processes including innate antiviral immnity, cell migration and chemotaxis. Acts as a 'Lys-63'-specific ubiquitin ligase for MAPK1/ERK2 and MAPK3/ERK1, promoting their activation by facilitating their interaction with MAP2K1 and MAP2K2. Also plays a role in cell migration and chemotaxis by acting as a stable focal adhesion component upon recruitment by multi-adapter protein paxillin/PXN. Functions in the RIGI-mediated interferon induction pathway upstream or at the level of MAVS. Inhibits NF-kappa-B activation by turnover of 'Lys-63'-linked ubiquitination of MAP3K7/TAK1. Mechanistically, prevents TRIM8 cytoplasmic translocation and thus inhibits TRIM8-mediated 'Lys-63'-linked polyubiquitination of MAP3K7/TAK1 in the cytoplasm. Also plays an important regulatory effect on the activation of hepatic stellate cells (HSCs).
Synonyms: RNF93; ZNF178; ZNFB7
Tractability: No criterion of Open Targets' tractability assessment is met for any kind of drug.
Gene: Protein-coding gene on chromosome 6 (30,163,194 to 30,173,160, forward strand). Ensembl gene ENSG00000204610.
Subcellular location: Cytoplasm; Nucleus; Cell junction, focal adhesion
Subcellular location (Human Protein Atlas): Cytosol; Centriolar satellite
Gene Ontology:
Molecular function: molecular sequestering activity; protein binding; transcription coactivator activity; ubiquitin protein ligase activity; metal ion binding; zinc ion binding
Biological process: antiviral innate immune response; negative regulation of intracellular transport of viral material; negative regulation of non-canonical NF-kappaB signal transduction; positive regulation of RIG-I signaling pathway; positive regulation of type I interferon production; suppression of viral release by host; innate immune response; mesodermal cell fate determination; positive regulation of DNA-templated transcription
Cellular component: cytoplasm; nucleus; focal adhesion
Genetic constraint (gnomAD): Loss-of-function variants: 36 observed, 35.61 expected, observed/expected ratio (o/e) 1.01, 90% interval 0.77 to 1.34. The upper end of that interval is the gene's LOEUF score, 1.34, which puts it in group 5 of 6, group 1 being the genes least tolerant of losing a copy. Missense variants: 590 observed, 578.55 expected, observed/expected ratio (o/e) 1.02, 90% interval 0.95 to 1.09. Synonymous variants: 252 observed, 240.82 expected, observed/expected ratio (o/e) 1.05, 90% interval 0.94 to 1.16.
Homologues: Orthologues: chimpanzee TRIM15 (99% identical), macaque TRIM15 (97% identical), pig TRIM15 (82% identical), rabbit TRIM15 (82% identical), rat Trim15 (47% identical), mouse Trim15 (46% identical). Paralogues in human: TRIM10 (44% identical), TRIM26 (37% identical), TRIM27 (32% identical), TRIM39 (31% identical), TRIM41 (30% identical), TRIM11 (29% identical), TRIM21 (29% identical), TRIM4 (28% identical), TRIM58 (28% identical), TRIM7 (28% identical), TRIM69 (26% identical), TRIM38 (26% identical), and 68 more.
Diseases named in the same sentence as TRIM15 in open-access papers:
TRIM15 is named in the same sentence as 28 diseases in open-access papers, as found by Europe PMC text mining. Sharing a sentence is not in itself a finding about the gene and the disease. The quoted sentences say what the papers report.
pancreatic cancer (7 papers, 2022 to 2026). "In pancreatic ductal adenocarcinoma, ubiquitination and degradation of ApoA1 mediated by TRIM15 can promote the invasion and metastasis of pancreatic cancer cells." (PMID 38212711, 2024). "We previously reported that TRIM15 targets APOA1 for degradation to promote the malignant progression of pancreatic cancer cells." (PMID 36670097, 2023). "Dysregulation of TRIM15 contributes to tumor progression in pancreatic cancer and non-small cell lung cancer." (PMID 36670097, 2023). "Additionally, TRIM15 promotes the invasion and metastasis of pancreatic cancer cells by mediating APOA1 ubiquitination and degradation." (PMID 35534896, 2022). "In addition, we found that TRIM15 might be involved in the regulation of lipolysis in adipocytes, which was consistent with our previous finding that TRIM15 targets APOA1 for degradation in pancreatic cancer." (PMID 36670097, 2023). "We previously reported that TRIM15 promotes APOA1 ubiquitination and degradation in pancreatic cancer." (PMID 36670097, 2023). "TRIM15 could regulate the Wnt/β-catenin signaling pathway and Keap1-Nrf2 pathway and mediate the ubiquitination of APOA1 and ERK to promote the development and progression of cancers such as non-small cell lung cancer, esophageal squamous cell carcinoma, and pancreatic cancer." (PMID 36189312, 2022).
gastric cancer (6 papers, 2014 to 2024). A primary or metastatic malignant neoplasm involving the stomach. "Evidence suggests that TRIM15 is a potential diagnostic marker of gastric cancer that affects DNA methylation patterns." (PMID 35534896, 2022). "Importantly, a recent study has found that the expression of TRIM15 is an independent risk factor of prognosis in gastric cancer patients." (PMID 36661663, 2022). "MEF2C and TRIM15 have previously been reported to be associated with gastric cancer." (PMID 36661663, 2022). "In contrast, TRIM15 was found to be downregulated in colon and gastric cancers and to exert an antitumor effect by inhibiting cell migration and invasion." (PMID 36670097, 2023). "The mean methylation levels of gastric cancer tissues were higher than those of normal gastric tissues for two sites (TRIM15 and ITGAM) and lower for two sites (MSX2 and FAM38A), which were consistent with the results of the microarray analysis." (PMID 24944662, 2014). "qPCR results showed that the expression levels of ITGAM, MSX2 and FAM38A were upregulated in gastric cancer tissues, while the expression level of TRIM15 was downregulated (P<0.05)." (PMID 24944662, 2014). "Moreover, specifically abnormal hypermethylation on TRIM15 has been detected in the gastric cancer genome, confirming the potential of TRIM15 methylation as a candidate signature for gastric cancer diagnosis." (PMID 32528944, 2020). "Analysis of the results identified TRIM15, ITGAM, MSX2 and FAM38A as possible candidate sites clinically useful for the diagnosis and treatment of gastric cancer." (PMID 24944662, 2014). "Interestingly, TRIM15 and TRIM16 not only show higher expression in gastric cancer tissues, promoting cancer progression, but also exhibit lower expression in some studies, where they inhibited cancer progression." (PMID 39768197, 2024). "TRIM15, ITGAM, MSX2 and FAM38A may be candidate genes for diagnosing gastric cancer." (PMID 24944662, 2014).
colon cancer (4 papers, 2017 to 2025). "TRIM15 contributes to various types of digestive system tumor, including colon tumor and gastric adenocarcinoma." (PMID 32528944, 2020). "A component of focal adhesion, TRIM15, has been found to function as a tumor suppressor in colon cancer." (PMID 29100272, 2017). "Notably, TRIM15 is also a Wnt target gene that forms a positive feedback loop in colon cancer cells." (PMID 41461634, 2025). "Five TRIM expression was significantly upregulated (TRIM14, TRIM15, TRIM24, TRIM29, and TRIM31), and the other five TRIM genes showed decreased expression (TRIM1, TRIM3, TRIM9, TRIM22, and TRIM73) in both colon cancer (COAD) and rectal cancer (READ)." (PMID 38769340, 2024).
esophageal squamous cell carcinoma (3 papers, 2022 to 2023). Esophageal squamous cell carcinoma (ESCC) is a type of esophageal carcinoma (EC) that can affect any part of the esophagus, but is usually located in the upper or middle third. "Knockdown of TRIM15 in esophageal squamous cell carcinoma (ESCC) cells significantly inhibited the proliferation, migration and invasion of cells by suppressing the Wnt/β-catenin signaling pathway." (PMID 36249749, 2022). "Additionally, inhibiting TRIM15 suppressed the proliferation, migration and invasion of esophageal squamous cell carcinoma cells." (PMID 36670097, 2023).
non-small cell lung carcinoma (3 papers, 2022 to 2023). A group of at least three distinct histological types of lung cancer, including non-small cell squamous cell carcinoma, adenocarcinoma, and large cell carcinoma. "TRIM15 was found to be overexpressed in non-small cell lung cancer and to correlate with unfavorable patient prognoses." (PMID 36670097, 2023).
liver cancer (2 papers, 2023 to 2026). An epithelial or non-epithelial malignant neoplasm that arises from the liver. "Together, our data suggested that LASP1 is the key mediator through which TRIM15 modulates sorafenib sensitivity in liver cancer cells." (PMID 36670097, 2023). "Then, we also demonstrated that treatment with FOXO1 inhibitors downregulated TRIM15 expression in liver cancer cells." (PMID 36670097, 2023). "In this study, we found that TRIM15 was abnormally upregulated in liver cancer cells after treated with TKIs and that this upregulation of TRIM15 contributed to TKI resistance in liver cancer cells." (PMID 36670097, 2023). "Then, the results of in vitro and in vivo cell proliferation assays indicated that inhibition of TRIM15 expression enhanced the antitumor effect of TKIs in liver cancer cells." (PMID 36670097, 2023). "Taken together, our data suggested that TKI-induced upregulation of TRIM15 is mediated by the AKT/FOXO1 axis in liver cancer cells." (PMID 36670097, 2023). "In our study, our results demonstrated that TRIM15 was abnormally upregulated in liver cancer cells after treated with TKIs and that this upregulation of TRIM15 contributed to TKI resistance in liver cancer cells." (PMID 36670097, 2023). "In addition, we found that TRIM15 overexpression prevented sorafenib-induced apoptosis in liver cancer cells." (PMID 36670097, 2023). "We found that TRIM15 interacted with LASP1 in liver cancer cells." (PMID 36670097, 2023). "Thus, our results indicated that TRIM15 regulates the nuclear translocation of LASP1 in liver cancer cells." (PMID 36670097, 2023). "Moreover, we demonstrated that FOXO1 silencing attenuated the increase in TRIM15 expression induced by regorafenib or sorafenib treatment in liver cancer cells." (PMID 36670097, 2023). "Since TRIM15 was upregulated in TKI-resistant liver cancer cells, we sought to determine whether TRIM15 participates in modulating the sensitivity of HCC cells to TKIs." (PMID 36670097, 2023). "Moreover, we demonstrated that TRIM15 induced the nuclear translocation of LASP1 by mediating its K63-linked polyubiquitination, which modulated sensitivity to TKIs by increasing the phosphorylation of AKT and the expression of Snail in liver cancer cells." (PMID 36670097, 2023). "Thus, we examined whether LASP1 is the key mediator of TRIM15-induced TKI resistance in liver cancer cells." (PMID 36670097, 2023). "TRIM15 silencing decreased the IC50 values of regorafenib and sorafenib in these liver cancer cells." (PMID 36670097, 2023). "In this part, we sought to determine how TRIM15 activates AKT signaling and promotes EMT in liver cancer cells." (PMID 36670097, 2023). "Taken together, these data suggested that the ubiquitination of LASP1 mediated by TRIM15 promoted LASP1 nuclear translocation to activate the AKT signaling pathway, which was responsible for inducing sorafenib resistance in liver cancer cells." (PMID 36670097, 2023). "In contrast, we demonstrated that overexpression of TRIM15 WT but not the catalytically dead mutant promoted the ubiquitination of LASP1 in liver cancer cells." (PMID 36670097, 2023). "In contrast, overexpression of wild-type TRIM15 but not the catalytically dead mutant activated AKT-mTOR signaling in liver cancer cells." (PMID 36670097, 2023). "Similarly, we found that knockdown of TRIM15 decreased the total ubiquitination and K63-linked ubiquitination but not K48-linked ubiquitination of LASP1 in liver cancer cells." (PMID 36670097, 2023).
lung carcinoma (2 papers, 2022). "Taken together, these findings indicated a strong correlation between high expression of TRIM15 and lung cancer malignancy, suggesting that TRIM15 may play a role in lung cancer development and progression." (PMID 35534896, 2022).
colon adenocarcinoma (1 paper, 2016). "TRIM15 expression is decreased in human colon adenocarcinoma compared with normal colon tissues; restoring expression in CC cells suppressed tumor growth in mice." (PMID 27888625, 2016).
colorectal cancer (1 paper, 2025). A primary or metastatic malignant neoplasm that affects the colon or rectum. "TRIM15 is highly expressed and is positively associated with β-catenin in colorectal cancer." (PMID 41461634, 2025). "Together, our study uncovers an important regulatory mechanism of Axin1 polymerization and implies that targeting TRIM15 provides a therapeutic strategy for colorectal cancer based on inhibiting Wnt signaling." (PMID 41461634, 2025). "Here, we reveal that TRIM15 interferes with the polymerization of Axin1, thereby promoting Wnt activation and colorectal cancer growth." (PMID 41461634, 2025). "Furthermore, conditional genetic ablation of Trim15 in mice inhibits tumor formation in both AOM/DSS-induced and ApcMin/+ colorectal cancer models." (PMID 41461634, 2025).
esophageal adenocarcinoma (1 paper, 2026). A malignant tumor with glandular differentiation arising predominantly from Barrett mucosa in the lower third of the esophagus. "The study identifies TRIM15 as a key driver in the development of obesity‐associated esophageal adenocarcinoma (EAC)." (PMID 41237333, 2026).
esophageal cancer (1 paper, 2019). A primary or metastatic malignant neoplasm involving the esophagus. "Among our methylation signatures, some genes have been reported in the onset and progression of BE and esophageal cancer or the prognosis of esophageal cancer, such as TRIM15, TACC3, SHANK2, and MCC." (PMID 31834866, 2019).
liver fibrosis (1 paper, 2024). "Some can play the same role in the face of the same disease, such as TRIM28 and TRIM38 in the progression of MAFLD and TRIM15 and TRIM47 in liver fibrosis." (PMID 39199424, 2024).
lung adenocarcinoma (1 paper, 2022). A carcinoma that arises from the lung and is characterized by the presence of malignant glandular epithelial cells. "We further examined the expression of TRIM15 by immunohistochemical staining on a human lung adenocarcinoma tissue array containing 98 tissue samples, whose clinicopathological features and complete follow-up data was performed." (PMID 35534896, 2022).
Obesity (1 paper, 2026). Accumulation of substantial excess body fat. "Here, the inflammation‐upregulated E3 ligase, tripartite motif 15 (TRIM15), is identified as a key driver of obesity‐associated EAC." (PMID 41237333, 2026). "Together, these results suggest that high inflammation levels lead to a significant upregulation of TRIM15 in obesity‐associated EAC tumor tissues, and knockdown of TRIM15 in EAC cells significantly inhibits the proliferative effects of obesity on EAC." (PMID 41237333, 2026). "Thus, a novel obesity‐associated TRIM15/YY2/FOXRED1 axis is identified that contributes to the proliferation of EAC." (PMID 41237333, 2026). "Thus, it is reasonable to hypothesize that TRIM15 plays a key role in obesity‐associated EAC progression." (PMID 41237333, 2026). "In summary, our study innovatively found that TRIM15 expression is upregulated in obesity‐associated EAC tumor tissues, emerging as a key molecule driving the proliferation stemming from obesity." (PMID 41237333, 2026).
tumor (11 papers, 2016 to 2026). "Among the ten tumor-related genes used in the risk model, TRIM15, NEK6, ISG15, RFC2, and NR1H3 were upregulated." (PMID 36189312, 2022). "Gain- and loss-of-function experiments showed that TRIM15 promoted tumor proliferation and metastasis by activating Nrf2 signaling." (PMID 35534896, 2022). "Correlation analysis revealed that high expression of TRIM15 in NSCLC tissues was significantly associated with a more aggressive tumor phenotype." (PMID 35534896, 2022). "TRIM15 is dysregulated in tumor cells and associated with tumorigenesis." (PMID 36670097, 2023). "Further studies revealed that TRIM15 promotes tumor progression by mediating the ubiquitination and subsequent degradation of YY2, disrupting lipid and energy metabolism regulation in EAC cells by inhibiting FOXRED1 transcription." (PMID 41237333, 2026). "Manipulation of TRIM15 expression dramatically weakens Wnt signaling, cell proliferation, and tumor growth." (PMID 41461634, 2025). "We demonstrated that the expression level of pAKT-S473, pFOXO1-S319, and TRIM15 were up-regulated in sorafenib resistant tumor samples from HCC patients compared to those in sorafenib sensitive group." (PMID 36670097, 2023). "We also noticed that knockdown of TRIM15 or treatment of sorafenib decreased the phosphorylation of AKT on Ser-473 in the tumor xenograft." (PMID 36670097, 2023). "In H1299 cells, TRIM15 knockdown significantly suppressed proliferation, migration, and invasion of tumor cells, and increased ROS levels, and these effects were recovered by Nrf2 rescue." (PMID 35534896, 2022). "To confirm these findings, we further examined the effects of TRIM15 expression on in vivo tumor growth and metastasis of NSCLC cells." (PMID 35534896, 2022). "Immunohistochemical staining further confirmed that TRIM15 was overexpressed in tumor tissues than matched surrounding tissues." (PMID 35534896, 2022). "Supporting a role of TRIM15 in tumorigenesis, TRIM15 depletion in H1299 cell line remarkably impaired tumor cell growth in vitro and in vivo." (PMID 35534896, 2022). "Structure–function evaluations also demonstrated that the tumor-promoting functions of TRIM15 depend on its E3 ubiquitin ligase." (PMID 35534896, 2022). "Consistently, Nrf2 is required for TRIM15 to facilitate tumor cell proliferation and metastasis in vitro and in vivo." (PMID 35534896, 2022). "In subcutaneous implantation nude mice models, overexpression of TRIM15 significantly promoted tumor growth compared with vector controls, and this effect was blocked when TRIM15 was co-expressed with shNrf2." (PMID 35534896, 2022). "In a set of complementary experiments, we clarified the role of TRIM15 knockdown on tumor growth in vivo." (PMID 35534896, 2022). "In support, other reports have shown that higher expression of TRIM15 is required for the survival of the mucosal epithelial tissues, particularly in the stomach and colon, where decreased expression promotes tumour growth in these organs." (PMID 31311100, 2019). "Western Blotting and RT‐qPCR analyses conducted on clinical tissue specimens, as well as immunohistochemistry (IHC) experiments performed on tissue microarray specimens (No.D046Ca01, Bioaitech, China), consistently demonstrated that the expression of TRIM15 was elevated in EAC tumor tissues." (PMID 41237333, 2026). "In addition, we have detected the FOXO1/TRIM15/LASP1/AKT loop in tumor samples from HCC patients with TKI sensitive or resistance." (PMID 36670097, 2023). "To further assess whether TRIM15 promotes tumor cell proliferation and metastasis dependent on Nrf2 signaling, we first silenced TRIM15 in the absence or presence of Nrf2 rescue." (PMID 35534896, 2022). "Downregulation of TRIM15 significantly inhibited tumor growth, whereas up-regulation of Nrf2 could promote the tumor growth of TRIM15 knockdown cells." (PMID 35534896, 2022).